STAT3 (signal transducer and activator of transcription 3)
Diseases named in the same sentence as STAT3 in open-access papers (continued):
Sharing a sentence is not in itself a finding about the gene and the disease.
glioblastoma (continued). "STAT3 are associated with glioblastoma invasion through Stat3/fibronectin pathway." (PMID 35052701, 2021). "Moreover, GP130 as well as its downstream STAT3 signaling was tightly associated with the stemness of glioblastoma stem like cells 20: GP130 blocking antibody drastically stem-like properties in GSCs." (PMID 31942189, 2020). "STAT3 is an important regulator of a number of anti-apoptotic genes, and its activity is associated with tumor growth, survival, angiogenesis, and metastatic processes, especially in glioblastoma progression." (PMID 27163161, 2016). "Also STAT3 has been linked to mesenchymal differentiation in glioblastoma cells, a phenotype of clinical aggressiveness and poor survival." (PMID 21052560, 2011). "In contrast, different studies indicated that Sorafenib induced an inhibition of STAT3 (phosphorylated signaltransducers and activators of transcription 3) that were associated with decreased levels of pAkt in glioblastoma cells, pancreatic cancer cell lines and neuroblastoma cells." (PMID 20950443, 2010). "Resveratrol improves the chemosensitivity of GBM (glioblastoma) cells to TMZ (temozolomide) by downregulating STAT3 activity and its associated gene products, resulting in decreased cell proliferation and migration, and increased apoptosis." (PMID 39769099, 2024). "For instance, the presence of exosomal miR-148a, known to target CAMD1 and boost signal transducer and activator of transcription 3 (STAT3) activity, has been linked to the advancement of glioblastoma multiforme (GBM)." (PMID 38398214, 2024). "As Stat3 signaling has been previously implicated in the mesenchymal transformation of adult glioblastomas, we hypothesized that the upregulation of mesenchymal markers by ACVR1 R206H in the presence of H3.1K27M is at least in part due to the activation of Stat3 signaling." (PMID 30833574, 2019). "Specific molecular characteristics provide distinct molecular glioblastoma subtypes, of which the mesenchymal subtype has been linked to a more aggressive and invasive tumor phenotype and is driven by alterations in master transcription factors such as STAT3, CEBP-β and NF-κB." (PMID 30621209, 2019). "Tumor electric field therapy (TEFT) inhibits glioblastoma progression by suppressing the TGF‐β/SMAD2/3/STAT3/C1R axis to reverse epithelial‐mesenchymal transition (EMT)." (PMID 41489302, 2026). "The first studied system encompassed patient-derived glioblastoma cell lines cultured in conditions supporting different levels of activation of the STAT3-Ser/Hes3 signaling axis involved in cancer growth regulation." (PMID 39960760, 2025). "This study evaluates the efficacy of Lipid Nanoparticles-EXOSOME COMPLEX STAT3-silencer treatment in reducing glioblastoma tumor growth by facilitating efficient small interfering RNA delivery and inhibiting STAT3 expression." (PMID 40427146, 2025). "Another factor associated with tumour progression is CD109 and the interaction of CD109 with STAT3 has been shown to drive glioblastoma stem cell plasticity and chemoresistance via STAT signalling." (PMID 40227788, 2025). "Genes such as VEGFA, PD-L1, PIK3CD, PRMT5, and STAT3 emerge as central nodes driving glioblastoma progression and therapeutic resistance." (PMID 41179304, 2025). "In glioblastoma, constitutive STAT3 signaling has been shown to support angiogenesis through the upregulation of vascular endothelial growth factor (VEGF)." (PMID 40075607, 2025). "The co-inhibition of Notch1 and JAK1/STAT3 has also been shown to disrupt the proliferation, migration, and invasion of glioblastoma cells and to inhibit the epithelial–mesenchymal transition." (PMID 40019515, 2025).
glioblastoma (continued). "Here in the study, Jmjd3 over expression suppressed glioblastoma stem cell proliferation and neurosphere formation and Jmjd3 knockdown reversed the neurosphere formation deficits induced by STAT3 inhibitors." (PMID 39951437, 2025). "GBP2 drives glioblastoma invasion via the Stat3/fibronectin pathway, linking immune signaling to extracellular matrix remodeling and physical tumor spread, facilitated by its homodimerization and cytoskeletal interactions." (PMID 40564939, 2025). "IL‐6/STAT3 signaling, in particular, plays a central role in glioblastoma progression by driving tumor cell survival and creating an immunosuppressive microenvironment." (PMID 41354084, 2025). "In conclusion, our study demonstrates that Calanquinone A exerts potent antitumor effects against glioblastoma multiforme by inhibiting cell viability, proliferation, and migration through suppression of the STAT3/c-Myc and STAT3/MMP9 signaling pathways." (PMID 40759869, 2025). "In cancers such as glioblastoma and pancreatic cancer, STAT3 activation supports CSC properties, including self-renewal and resistance to conventional therapies." (PMID 40075607, 2025). "STAT3 has been shown to play a neuroprotective role against glutamate-induced excitotoxicity in primary cultures of dorsal root ganglion neurons and glioblastoma cells." (PMID 40802001, 2025). "In glioblastoma, curcumin inhibited STAT3 phosphorylation, reducing MMP-9, Snail, and Twist expression, and suppressed MMPs via MAPK inhibition." (PMID 40430278, 2025). "STAT3 is involved in the expression of the autophagy-related gene ATG5 in Glioblastoma multiforme stem cells." (PMID 40727105, 2025). "RBPJ, a crucial TF in Notch signaling was found to promote glioblastoma progression through the IL-6/STAT3 axis in vitro." (PMID 40660393, 2025). "OSMR promotes the JAK/STAT3 signaling pathway, which promotes malignant glioblastoma growth and macrophages M2 polarization." (PMID 40161370, 2025). "GBP2’s anti-tumor effects in breast cancer hinge on mitochondrial dynamics and autophagy, while its pro-tumor role in glioblastoma leverages fibronectin remodeling and Stat3 activation, reflecting TME-specific signaling." (PMID 40564939, 2025). "The inhibition of STAT3 signaling by sorafenib contributes to growth arrest and induction of apoptosis in glioblastoma cells." (PMID 40076810, 2025). "Several studies have also shown that upregulated STAT3 contributes to poor prognosis for patients with glioblastoma, especially due to the role STAT3 plays in immune evasion." (PMID 40075607, 2025). "SHF is a tumor suppressor of glioblastoma and inhibits glioblastoma progression by negatively regulating STAT3 dimerization." (PMID 40124621, 2025). "In glioblastoma models, STAT3 inhibition has been found to enhance the effects of radiation therapy by disrupting DNA repair and survival pathways." (PMID 40166646, 2025). "For instance, EZH2 enhances STAT3 activity by increasing STAT3 tyrosine phosphorylation in glioblastoma." (PMID 39636550, 2025). "Signal Transducer and Activator of Transcription 3 (STAT3) plays a crucial role in glioblastoma progression, making it a promising therapeutic target." (PMID 40427146, 2025). "In glioblastoma, it activates JNK/STAT3 in glioblastoma stem cells (GSCs), enhancing self-renewal and tumor growth." (PMID 40361374, 2025). "In these experiments, ADGRL4 overexpression in a glioblastoma cell line activated JAK/STAT3 signalling, whereas ADGRL4 knockdown attenuated it23." (PMID 41469374, 2025). "IL6 is known to promote tumor proliferation and survival in glioblastoma through the JAK/STAT3 signaling pathway." (PMID 41282050, 2025). "This, in turn, can worsen IL-6-mediated pathological effects through the IL-6/JAK/STAT3 signaling pathway, which is a significant driver of glioblastoma." (PMID 40843259, 2025). "The in vitro data showed a significant reduction in STAT3 expression, resulting in impaired proliferation of U87 glioblastoma cells." (PMID 40427146, 2025).
glioblastoma (continued). "The results indicated that while both siRNAs effectively reduced STAT3 expression, SiRNA 2 exhibited a more pronounced knockdown effect, leading to greater suppression of glioblastoma cell proliferation." (PMID 40427146, 2025). "The expression of US28 in glioblastoma cells increases their growth potential, leading to the formation of larger tumours, which is mechanistically mediated through enhanced IL-6/STAT3 signalling." (PMID 41194660, 2025). "This transition was mediated by the secretion of oncostatin M by macrophages, which interacted with its receptors on glioblastoma cells, activating the signal transducer and activator of transcription 3 (STAT3) signaling pathway." (PMID 40083710, 2025). "Collectively, the introduction of hybrid nanoparticles mediated site‐specific STAT3 gene knockout for advanced antiangiogenic and immune glioblastoma therapy." (PMID 38923275, 2024). "In a xenograft model, silencing miR-21 led to a significant inhibition of tumor growth and a decrease in STAT3 and hTERT expression, indicating that miR-21 regulates STAT3-mediated hTERT expression to modulate glioblastoma cell growth." (PMID 39114567, 2024). "IL-6 derived from glioblastoma induces PD-L1 expression on bone marrow cells via a STAT3-dependent mechanism, therapeutic blockade of IL-6 signaling inhibits tumor growth and improves survival rates." (PMID 38762484, 2024). "In glioblastoma, bFGF is upregulated by JAK/STAT3 activation, and induced by a glioblastoma stem cell-derived protein, Interferon-Induced Transmembrane Protein 3 (IFITM3), which subsequently promotes angiogenesis and metastasis." (PMID 39796710, 2024). "Proteasomal inhibitors bortezomib or marizomib induce caspase 9 and increase PIAS3 expressions that initiated apoptosis and inhibit STAT3 activity in glioblastoma cells." (PMID 38590645, 2024). "Exosomes derived from glioblastoma stem cells further enhance immunosuppression by upregulating phosphorylated STAT3, thus promoting macrophage polarization to M2 macrophages and increasing PD-L1 expression." (PMID 38762484, 2024). "In the case of Smad6, MH2 domain and PIAS3 ring domain are responsible for their interaction that degrades PIAS3 and promotes STAT3 activity in glioblastoma." (PMID 38590645, 2024). "STAT3 inhibition suppressed the enhanced migrative ability induced by glioblastoma cells overexpressing TSPAN6 in HUVEC cells." (PMID 38725860, 2024). "Glioblastoma stem cells derived exosomes release STAT3 and facilitate the accumulation of PD-L1 and M2 macrophage which eventually trigger the immunosuppressive microenvironment." (PMID 38245798, 2024). "Nuclear autoantigenic sperm protein (NASP) plays a crucial role in glioblastoma progression and radioresistance, promotes DNA repair, and activates the STAT3 signaling pathway through ANXA2." (PMID 38605477, 2024). "In contrast, TSPAN6 overexpression promoted the activation of STAT3 via enhancing the phosphorylating STAT3 in glioblastoma cells." (PMID 38725860, 2024). "Together, these findings suggest that LDHA-directed ERK pathway regulates HOXA9, YAP1, and STAT3 transcription factors and/or signaling pathways in glioblastoma cells and GSCs." (PMID 38443336, 2024). "Bradykinin, via the bradykinin 1 receptor, promotes the expression of interleukin-8, leading to translocation into the nucleus of phosphorylated STAT3 and acetylated SP-1, favoring the migration of glioblastoma cells." (PMID 39063232, 2024). "QUE has been demonstrated to decrease IL-6 levels in a dose-dependent mode through STAT3 activation in T98G and U87 glioblastoma cells." (PMID 39202863, 2024). "Western blot analysis confirmed that the combination therapy markedly reduced STAT3 expression in glioblastoma multiforme cells compared to Temozolomide alone." (PMID 39421869, 2024). "This chronic low-grade inflammation contributes to an aggressive glioblastoma phenotype by activating pathways such as NF-κB and STAT3, which drive tumor progression and survival." (PMID 39518104, 2024).
glioblastoma (continued). "Meanwhile, STAT3 inhibitor niclosamide suppressed the enhanced migrative ability induced by glioblastoma cells overexpressing TSPAN6 in HUVEC cells." (PMID 38725860, 2024). "Since it can suppress Jak2/Stat3, an important cancer cell proliferation pathway in glioblastoma, the combination of NP and DX can be used as an alternative treatment agent." (PMID 39459502, 2024). "Neurotensin controls, via activation of the interleukin-8/ERK/CXXC1/STAT3 pathway, the stem-like traits of glioblastoma stem cells." (PMID 39063232, 2024). "For example, cardamonin inhibits glioblastoma stem cell proliferation by suppressing the STAT3 pathway, which subsequently prevents the activation of Bcl-2, survivin, and VEGF." (PMID 39877386, 2024). "RBM15 deficiency decreased m6A modification of DLG3 mRNA and subsequently induced GSC proneural-to-mesenchymal transition by activating the STAT3 pathway to support glioblastoma progression and radioresistance." (PMID 38951882, 2024). "For example, icaritin inhibits the survival and glycolysis of glioblastoma (GBM) cells through the IL-6/STAT3 pathway." (PMID 38495094, 2024). "Our findings are consistent with a previous study demonstrating that targeting STAT3 leads to the downregulation of the expression of the STAT3 protein, promotes the degradation of STAT3 ubiquitination, and inhibits cell metastasis in human glioblastoma cells." (PMID 39195486, 2024). "This interaction results in stabilized STAT3-chromatin interactions and subsequent activation of STAT3 downstream signaling, thereby intensifying the oncogenic activity of the EGFR/STAT3 pathway in glioblastoma." (PMID 39160596, 2024). "Specifically, STAT3 was identified as an invasion-deterministic transcription factor in glioblastoma based on transcriptome analysis of GBM TSs and paired tissues." (PMID 38675489, 2024). "In glioblastoma cell lines, RHOB knockdown has been shown to cause decreased cytokine-induced STAT3 activation and impaired STAT3 activity." (PMID 38166692, 2024). "Another mechanism by which BK regulates migration in glioblastoma cells is the activation of STAT3 and the promotion of its interaction with SP-1." (PMID 39519260, 2024). "In this study, Jak2/Stat3 expressions were examined for the first time in the glioblastoma cell line (U87) after a separate and combined application of NP and DX." (PMID 39459502, 2024). "Mechanistically, our study demonstrated that these two chemokines are regulated by LDHA/lactate-induced activation of YAP1 and STAT3 in glioblastoma cells." (PMID 38443336, 2024). "Vehicle control, NP and DX agents were applied individually and in combination with glioblastoma cells; the U87 cell line and Jak2 and Stat3 gene expressions were detected after 48 h." (PMID 39459502, 2024). "RBM8A can enhance the invasive capabilities of glioblastoma by stimulating the transcriptional activation of Notch1 and STAT3, thereby activating the Notch/STAT signaling pathway." (PMID 38672496, 2024). "Subsequent analysis revealed that glioblastoma cells treated with CuI had lower levels of phosphorylated-STAT3, accompanied by increased apoptosis and cell cycle arrest." (PMID 38397437, 2024). "Stellettin B appears to act mainly due to the induction of autophagy and apoptosis by interfering with the PI3K/Akt, Stat3, and mTOR signaling pathways in glioblastoma and chronic myeloid leukemia cells." (PMID 38667760, 2024). "Taken together, our results indicate that co-administering TMZ with a JNK or STAT3 inhibitor holds promise as a potentially effective treatment for glioblastoma." (PMID 37759808, 2023). "Previous investigations have provided evidence that JSI-124 possesses the capability to hinder the JAK/STAT3 pathway across different cancer categories, including glioblastoma." (PMID 38001999, 2023). "Several subnetworks include pathways related to cancer, such as already mentioned subnetwork #4 and subnetwork #14, as well subnetwork as #13 (STAT3 signaling and glioblastoma signaling)." (PMID 36829477, 2023).
glioblastoma (continued). "It has been documented that SH2B3 contributes to glioblastoma progression by transducing IL-6/gp130/STAT3 signaling." (PMID 37426414, 2023). "Specifically, JSI-124 can downregulate the levels of phosphorylated-STAT3, leading to apoptosis induction in glioblastoma cells." (PMID 38001999, 2023). "And this study suggests that a combination of TMZ and an inhibitor of JNK kinase or STAT3 is a potentially effective strategy for glioblastoma treatment." (PMID 37759808, 2023). "Radiation can further increase the interaction of the nuclear STAT3/ NFκB p65 complex with the proximal intron-1 region of the ICAM-1 gene in glioblastoma multiforme." (PMID 37821959, 2023). "It has been reported that the CD109/STAT3 signaling axis is a mediator of chemoresistance in glioblastoma stem cells." (PMID 37373457, 2023). "Preferential expression of OTULIN in glioblastoma stem-like cells (GSCs) removes linear ubiquitin conjugated on STAT3, leading to persistent STAT3 signaling, which maintains the stemness and self-renewal of GSCs." (PMID 38017534, 2023). "Recently, it was reported that STAT3 inhibition by the inhibitor WP1066 resulted in increased expression levels of miR-181a-5p in glioblastoma multiforme cell lines." (PMID 37490712, 2023). "In a study with glioblastoma cell lines U251-MG and U87-MG, increased phosphorylation of p65 was observed after treatment with STAT3 inhibitor JSI-124, which is suggestive of a similar mechanism being activated in breast tumor cells." (PMID 37005447, 2023). "Combined profiling and functional studies demonstrate that LDHA-directed ERK pathway activates YAP1/STAT3 transcriptional co-activators in glioblastoma cells to upregulate CCL2 and CCL7, which recruit macrophages into the tumor microenvironment." (PMID 37886538, 2023). "Our previous publication showed that TRPM7 activates STAT3 through the phosphorylation of STAT3 at Tyr705 and increases glioblastoma stemenss; here, we further detected the nuleocytoplasmic distribution of activated STAT3 upon expression of TRPM7." (PMID 37642779, 2023). "The levels of phosphorylated STAT3 have been evaluated as a prognostic biomarker, and the levels of phosphorylated STAT3 at Y705 have been shown to increase the radiosensitization of glioblastoma multiforme cells." (PMID 36977736, 2023). "MGMT and phosphorylated-STAT3 levels increase in recurrent tumors compared to primary glioblastoma patients." (PMID 38264122, 2023). "FAK has been previously linked to the JAK/STAT3 pathway, promoting cell motility and cellular signalling in glioblastoma cells, whilst the inhibition of STAT3 repressed the invasive capabilities of astrocytoma cells." (PMID 37896150, 2023). "Prior reports show that STAT3 up-regulates ID1 expression by binding to the ID1 promoter in the glioblastoma." (PMID 37373188, 2023). "In glioblastoma stem cells (GSCs), it had been reported that local anesthetics suppressed the STAT3 signaling pathway by inhibiting ZDHHC15." (PMID 37161425, 2023). "Antisense oligonucleotide STAT3 transfected into U251 cells can inhibit the expression of STAT3, reduce the content of STAT3, and inhibit the proliferation and invasion of glioblastoma cells." (PMID 36923251, 2023). "A rational therapy for the treatment of glioblastoma would be the combination of temozolomide with the STAT3 inhibitor SBT-100, two anticancer compounds that penetrate the BBB." (PMID 36902166, 2023). "JSI-124 has been identified as a trigger for apoptosis in glioblastoma cells through the modulation of the JAK2/STAT3 signaling pathway." (PMID 38001999, 2023). "TRIM8 re-localizes from the cytoplasm of healthy neurons to the nucleus in GBM cells to establish a stem-like phenotype, with an increase in malignancy and glioblastoma stem cell markers, such as STAT3, SOX2, Nestin, and Nanog." (PMID 38115822, 2023).